NFKB1 (nuclear factor kappa B subunit 1)
Diseases named in the same sentence as NFKB1 in open-access papers (continued):
Sharing a sentence is not in itself a finding about the gene and the disease.
bladder cancer (255 papers, 2007 to 2026). "These variables were further adjusted in the multivariate logistic regression analysis to assess the main effect of the -94 ins/del ATTG polymorphism in NFKB1 promoter on bladder cancer risk." (PMID 23977085, 2013). "Genotype and allele frequencies of the NFKB1 promoter -94 ins/del ATTG polymorphism among the bladder cancer cases and controls." (PMID 23977085, 2013). "We further assessed the effect the -94 ins/del ATTG polymorphism in NFKB1 promoter on bladder cancer risk stratified by age, sex, smoking status, drinking status, and self-reported family history of cancer." (PMID 23977085, 2013). "Logistic regression was used to assess the association between the polymorphism and bladder cancer risk, and quantitative real-time polymerase chain reaction was used to determine NFKB1 mRNA expression." (PMID 23977085, 2013). "In this study, we identified an association between the -94 ins/del ATTG polymorphism in NFKB1 promoter and bladder cancer risk in a Chinese population." (PMID 23977085, 2013). "In conclusion, we identified an association between the -94 insertion/deletion ATTG polymorphism in NFKB1 promoter and bladder cancer risk in a Chinese population." (PMID 23977085, 2013). "In the present study, we hypothesized that the -94 ins/del ATTG polymorphism in NFKB1 promoter is associated with bladder cancer risk." (PMID 23977085, 2013). "In conclusion, the -94 ins/del ATTG polymorphism in NFKB1 promoter may contribute to the etiology of bladder cancer in the Chinese population." (PMID 23977085, 2013). "The associations between NFKB1 promoter –94 ins/del ATTG polymorphism and the development of bladder cancer." (PMID 23977085, 2013). "The expression of NFKB1 mRNA in bladder cancer tissues with homozygous insertion genotype was higher than that with deletion allele." (PMID 23977085, 2013). "Stratification analyses between NFKB1 promoter –94 ins/del ATTG polymorphism and risk of bladder cancer." (PMID 23977085, 2013). "NFKB1 promoter –94 ins/del ATTG polymorphism and clinicopathological characteristics in patients with bladder cancer." (PMID 23977085, 2013). "The amount of relative NFKB1 mRNA in bladder cancer tissues obtained from the homozygous insertion genotype (n = 8) was higher than that in tissues from the ins/del + del/del genotype (n = 27) (P = 0.025), even though there was significant overlap between the two groups." (PMID 23977085, 2013). "Although, prior studies have shown significant association of the NFKB1 polymorphism with carcinoma of urinary bladder, prostate, cervix and nasopharynx, no role of the polymorphism in ESCC susceptibility was found in the present study." (PMID 24324738, 2013). "It has been suggested that METTL3 promotes bladder cancer cell proliferation and invasion by modulating pri-miR-221/222 and the AF4/FMR2 family member 4 (AFF4)/nuclear factor kappa B subunit 1 (NF-κB)/MYC pathway in an m6A-dependent manner." (PMID 32709063, 2020).
liver cancer (255 papers, 2009 to 2026). An epithelial or non-epithelial malignant neoplasm that arises from the liver. "Beyond the PI3K/AKT core, network pharmacology analysis uncovered 185 overlapping targets, including inflammatory regulators NFKB1 and RELA, suggesting that cinnamic acid may enhance its anti-liver cancer effect by inhibiting the tumor-associated inflammatory microenvironment." (PMID 40872596, 2025). "However, also in correlation with liver cancer development, mice lacking Nfkb1 develop spontaneous invasive GC." (PMID 30205516, 2018).
osteosarcoma (251 papers, 2006 to 2026). A usually aggressive malignant bone-forming mesenchymal neoplasm, predominantly affecting adolescents and young adults. "Nuclear factor-κB1 (NFκB1) gene plays an important role in the pathogenesis of osteosarcoma, which indicates that osteosarcoma is closely related to the gene polymorphism of NFKB1." (PMID 30936265, 2019). "And there were 38 endogenous genes (including ARF1, HSP90AB1, and TUBA1B), 53 TFs (including E2F1, NFKB1, and EGR1), and 858 ncRNAs (including MALAT1, miR-590-3p, and TUG1) were considered as key regulators of osteosarcoma through a series of function enrichment analysis and network analysis." (PMID 30936265, 2019). "On the other hand, both NFKB1 and EGR1 have been found to regulate the two dysfunction modules, which may also be key regulators involved in the pathogenesis of osteosarcoma." (PMID 30936265, 2019).
osteoporosis (248 papers, 2010 to 2026). A condition of reduced bone mass, with decreased cortical thickness and a decrease in the number and size of the trabeculae of cancellous bone (but normal chemical composition), resulting in increased fracture incidence. "NFKB1, IL-1β, and RelA had an increased binding potency which mainly explains Quercetin’s anti-osteoporosis activity." (PMID 36839278, 2023). "Furthermore, 36 hub genes of XLGB, such as EGF, EGFR, MTOR, MAPK14 and NFKB1, were considered potential therapeutic targets, suggesting the underlying mechanisms of XLGB acting on osteoporosis." (PMID 32620113, 2020). "Therefore, the IL1B and NF-κB (RelA and NFKB1) signaling pathways are key targets to treat osteoporosis phenotypes." (PMID 35888070, 2022).
cardiac hypertrophy (241 papers, 2009 to 2026). "Moreover, age‐associated phenotypes such as increased cardiac hypertrophy, lung emphysema and skin epidermal thinning observed in nfκb1−/− mice were ameliorated following rapamycin supplementation." (PMID 30468013, 2019). "Lung airspace enlargement, indicative of emphysematous‐like changes, epidermal thinning of the skin and increased cardiac hypertrophy which occur during normal aging and prematurely in nfκb1−/− mice, was significantly reduced following a rapamycin treatment." (PMID 30468013, 2019).
pulmonary fibrosis (241 papers, 2010 to 2026). Chronic progressive interstitial lung disorder characterized by the replacement of the lung tissue by connective tissue, leading to progressive dyspnea, respiratory failure, or right heart failure.
type 2 diabetes (240 papers, 2006 to 2026). "We previously showed that hypomethylation of the IL1RN and NFKB1 gene promoters is associated with dysregulation of the IL-1β/IL-1Ra axis in type 2 diabetes." (PMID 40821781, 2025). "We have recently demonstrated that NFKB1 variation was an independent risk factor for developing type 2 diabetes, while the NFKBIZ variant was an independent risk factor for developing early-onset coronary artery disease." (PMID 31815120, 2019). "NFKB1 can increase the susceptibility of type 2 diabetes and kidney disease." (PMID 30521536, 2018). "NFKB1 can increases the susceptibility of type 2 diabetes and kidney disease." (PMID 30521536, 2018). "Type 2 diabetes is associated with increased APOE, BAX, MMP1, NFKB1, PDGFB, SPP1, and TGFB2." (PMID 35153741, 2021). "TNF, NFkB complex, NFkBIA, NFkB1 and RELA were also involved in type 2 diabetes signaling." (PMID 37047308, 2023).
myocardial infarction (236 papers, 2009 to 2026). Gross necrosis of the myocardium, as a result of interruption of the blood supply to the area, as in coronary thrombosis. "NFKB1 gene rs28362491 ins/del variation correlates to increased susceptibility to myocardial infarction among Chinese Han patients." (PMID 36248430, 2022). "Studies had shown that the -94 ins/del ATTG NFκB1 gene variant might lead to a decrease in myocardial infarction sensitivity by a potential reduction in activation of NFκB, which in turn was associated with a decrease in plasma inflammatory markers." (PMID 33879068, 2021). "The NFKB1-94ins/del ATTG polymorphism may reduce the susceptibility to myocardial infarction by decreasing activated NF-κB, which is in turn correlated with the reduction of plasma inflammatory markers." (PMID 29348768, 2017).
Hypertension (225 papers, 2009 to 2026). The presence of chronic increased pressure in the systemic arterial system. "RUNX1 in monocytes/macrophages is associated with the development of IA via the expression of NFKB1 among patients with hypertension." (PMID 35655614, 2022). "NFKB1 is involved in hypertension progression by affecting vascular endothelial function via the regulation of downstream NOS3 gene expression." (PMID 35655614, 2022). "Among patients with hypertension, RUNX1 in monocytes and macrophages was associated with a higher risk of IA through its regulation of NFKB1." (PMID 35655614, 2022). "After adjustment for age, smoking, DM, hypertension, glucose, and LDL-C, Cox regression analysis showed that the NFKB1 DD mutant was associated with a higher incidence of MACCE (DD versus II: adjusted OR = 2.578, 95%CI = 1.64–4.05, P = 0.003)." (PMID 36317060, 2022). "The results indicate that in the Ang II-induced hypertension group, the expression levels of TNF, NFKB1, MAPK3, PTGS2, and RELA were markedly elevated compared to the control group, while the expression levels of HSP90AA1, HSP90AB1, PPARG, SIRT1, MAPK1, and PRKCA were significantly decreased." (PMID 39592923, 2024). "Our analyses showed that TNF, HSP90AA1, NFKB1, PPARG, SIRT1, PTGS2, and RELA might be α-MG’s potential therapeutic targets for hypertension, laying groundwork for further investigation into its pharmacological mechanisms and clinical uses." (PMID 39592923, 2024).
acute kidney injury (214 papers, 2009 to 2026). Sudden and sustained deterioration of the kidney function characterized by decreased glomerular filtration rate, increased serum creatinine or oliguria. "Sun and colleagues were interested in studying single nucleotide polymorphisms (SNPs) (rs41275743 and rs4648143) in the 3′-untranslated region of the nuclear factor-kappaB gene NFKB1 and the risk of acute kidney injury (AKI) in sepsis." (PMID 36831207, 2023). "In the present study, we investigated the association of 12 polymorphisms in six inflammatory-response genes (TNF, IL6, IL10, IL18, NFKB1 and NFKBIA) with risk of acute kidney injury (AKI) in children." (PMID 30429237, 2018).
Immunodeficiency (214 papers, 2007 to 2026). Failure of the immune system to protect the body adequately from infection, due to the absence or insufficiency of some component process or substance. "The methods of our analyses pave the way for the evaluation of more NFκB1 mutations and possibly the categorization of NFκB1 mutations into the variety of immunodeficiencies, inflammatory diseases, and cancers that they cause." (PMID 37895204, 2023). "More recently, genomic sequencing has revealed loss of function mutations in the NFKB1 gene as the most common monogenic cause of common variable immunodeficiencies in Europeans." (PMID 34721373, 2021). "A recent study of Finnish families with loss of function mutations in NFKB1 identified miscodings affecting protein stability, defective subunit phosphorylation, and translocation of the nucleus causing a wide range of immune disorders." (PMID 34434197, 2021). "The key gene of this network is NFKB1, which is strongly associated with disease related to immunodeficiency." (PMID 33374967, 2020). "NFKB1 variants presented the most frequent known monogenic cause in our cohort and segregated with immunodeficiency in the families, though with an incomplete penetrance of the clinical manifestation." (PMID 31803180, 2019). "As generally seen with monoallelic and especially haploinsufficient immunodeficiencies, penetrance of disease manifestation is below 100% and age of onset is variable in individuals with NFKB1 mutations." (PMID 29403474, 2017). "Therefore, P1 was heterozygous for both the novel CXCR4 variant and the established pathogenic NFKB1 variant, consistent with a blended immunodeficiency phenotype." (PMID 40909287, 2025). "Among them, Nfkb1 is a widespread and important transcription factor involved in T cell activation, gene expression involved in a variety of biological functions such as immune regulation and cell adhesion, and is associated with a variety of immune diseases." (PMID 40256391, 2025). "LOF variants of NFKB1 typically lead to immune deficiency and/or autoinflammation." (PMID 38593810, 2024). "Loss-of-function (LOF) mutations in NFKB1, coding for p105, may cause common variable immunodeficiency due to dysregulation of nuclear factor kappa-light-chain-enhancer of activated B cells (NF-κΒ) pathway." (PMID 36892687, 2023). "Deleterious mutations in the N terminal part of p105, including frameshift and truncations, have been shown to cause (haplo) insufficiency, whereas examining the pathogenic relevance of a vast number of NFKB1 missense variants in patients with immunodeficiency remained scarce." (PMID 35003082, 2021). "NFKB1 loss-of-function mutations elicit a wide clinical phenotype with asymptomatic individuals at one end of the spectrum and patients with common variable immunodeficiency, combined immunodeficiency or autoinflammation at the other." (PMID 30761159, 2019). "Here, we identify a novel mutation of NFKB1 in a patient with combined immunodeficiency with impaired B and T cell functions and presentation with severe Epstein-Barr virus (EBV)-associated lymphoproliferation as a hitherto unrecognized clinical disease manifestation." (PMID 27338827, 2016). "Therefore, simultaneous gene mutations of the nonsense C6 and intronic NFKB1 were speculated to have contributed to the immunodeficiency in our case, with significant clinical implications." (PMID 39823049, 2024). "Monoallelic mutations in NFKB1 causing genetic or functional NF-κB1 haploinsufficiency have recently been reported to not only account for CVID-like B-cell deficiency, but a rather complex immunodeficiency-like profile including the emergence of combined B- and T-cell dysfunction." (PMID 29403474, 2017). "Since no diagnostic details are given, the exclusion of combined immune deficiencies involving T-cell immunity as well as B-cell failure, or known mutations in monogenic disease (e.g. CTLA4, LRBA, KMT2D, XIAP, RAG1, NFKB1) is unclear." (PMID 33329602, 2020).
Hepatic steatosis (195 papers, 2009 to 2026). Steatosis is a term used to denote lipid accumulation within hepatocytes. "The coactivator p300, a member of the HAT family, regulates transcription factors like nuclear factor kappa B subunit 1 (NF‐κB) and carbohydrate‐responsive element‐binding protein (ChREBP), which are central to lipid synthesis and inflammation in hepatic steatosis and HCC." (PMID 40693828, 2025).
Autoimmunity (187 papers, 2007 to 2026). The occurrence of an immune reaction against the organism's own cells or tissues. "Heterozygous LOF mutations in NFKB1 cause recurrent sinopulmonary infections, lymphoproliferation and autoimmunity." (PMID 38772735, 2024). "Since family members, carrying deleterious NFKB1 variants with moderate phenotype are at high risk for autoimmunity and malignancy, a closer follow-up for early initiation of IgG substitution therapy to prevent complications is strongly recommended." (PMID 35003082, 2021). "In two large cohorts of patients with NFKB1 variants, infections, autoimmunity, lymphoproliferation and malignancy were common clinical manifestations, with an age-dependent onset of respective symptoms." (PMID 33995346, 2021). "Almost all patients with alteration in NFKB1 causing p50 haploinsufficiency presented with diverse clinical manifestations, mainly autoimmunity, lymphoproliferative disorders, splenomegaly, CMV infections, and malignancies besides antibody deficiency." (PMID 35003082, 2021). "Loss-of-function of NFKB1 are the most common monogenic cause of common variable immunodeficiency in Europe associated with lymphadenopathy, splenomegaly and with age, autoimmunity and cancer." (PMID 34434197, 2021). "Especially, NFKB1 has been recently identified as a causal gene of autosomal dominant variable immunodeficiency-12, which shows features of autoimmunity." (PMID 29325558, 2018). "The association of NFKB1 indicates that the NF-κB downstream pathway is central to autoimmunity and the gene was represented by rs1314336 (pi = 6.0×10−4, 44 kb upstream)." (PMID 28081217, 2017). "In contrast, the maternal NFKB1 variant was associated with agammaglobulinemia and autoimmunity." (PMID 40909287, 2025). "The heterodimer composed of NFκB1/ RelA or NFκB1/c-Rel is predominant in different immune cells and plays a role in autoimmunity." (PMID 39058384, 2024). "MYD88 and NFKB1, central to toll-like receptor and NF-kB signaling, are therapeutic targets in cancer and autoimmunity, with inhibitors and antibodies that could be repurposed for NDs." (PMID 41153395, 2025). "NFKB1 regulates inflammatory and survival pathways, and its overactivation may lead to autoimmunity." (PMID 40906153, 2025). "Even though not related to autoimmunity, Bcl3 deficiency also resulted in resistance to skeletal muscle atrophy, a phenomenon that is phenotypically mimicked in p105/p50 (Nfkb1) knockout mice." (PMID 40359334, 2025). "NFKB1 haploinsufficiengcy was first described in 2015 in three families with common variable immunodeficiency (CVID), presenting heterogeneously with symptoms of increased infectious susceptibility, skin lesions, malignant lymphoproliferation and autoimmunity." (PMID 36203612, 2022). "NFKB1 haploinsufficiency was first described in 2015 in three families with common variable immunodeficiency (CVID), presenting heterogeneously with symptoms of increased infectious susceptibility, skin lesions, malignant lymphoproliferation and autoimmunity." (PMID 36203612, 2022). "NFKB1, known for its role in immune modulation and inflammation, was specifically active in Regulatory CD4+ T Cells, suggesting its contribution to immune tolerance and the prevention of autoimmunity in this subtype." (PMID 39877357, 2024). "Transgenic mice lacking the Nfκb1 (also known as p50) subunit of NF-κB did not acquire developmental abnormalities but did exhibit nonspecific responses to infection, such as autoimmunity." (PMID 35740465, 2022).
mastitis (183 papers, 2010 to 2026). Inflammation of breast tissue during lactation or postpartum due to an obstructed duct or infection. "As expected, previous data showed that NFKB1 and NFKB2 were upregulated in LPS- and LTA-induced mastitis in mammary epithelial cells, which was directly related to infection-induced inflammation during mastitis." (PMID 37620551, 2023). "LncRNAs such as LOC107133214, LOC104974443 and LOC101906793 can regulate the expression of inflammatory and cell death-related mRNAs such as IL-6, NFKB1 and TNFAIP3 and participate in the process of mastitis through NOD-like receptor, TNF, MAPK and other signaling pathways." (PMID 37845761, 2023). "In addition to TNFa and IL-1b, CASP1 and NFKB1 were found to be up-regulated in our study suggesting that TREM1 signaling may likely provide the link between TLR2- and NLR-mediated signal transduction in cytokine-induced inflammation during the initiation of host defense such as in mastitis." (PMID 24341851, 2013).